ALDH1A1 (aldehyde dehydrogenase 1 family member A1)
Diseases named in the same sentence as ALDH1A1 in open-access papers (continued):
Sharing a sentence is not in itself a finding about the gene and the disease.
cancer (continued). "Interestingly, disulfiram, a well-known treatment for alcohol abuse, has recently been suggested as a repurposed anti-cancer drug due to its inhibition of ALDH isoforms such as ALDH1A1, ALDH1A3, and ALDH2." (PMID 38612911, 2024). "In addition, we explore the stem cell marker aldehyde dehydrogenase 1 family member A1 (ALDH1A1) due to its recognized role in stemness and therapeutic resistance in several cancers." (PMID 38400679, 2024). "Further studies evaluating the biochemical pathways CD44 and ALDH1A1 in OS compared to other cancers may further elucidate critical differences that affect tumor behavior." (PMID 38371078, 2024). "There are many markers that could differentiate CSCs from NSCs such as CD44, CD133, CD24, EpCam, ALDH1A1, etc.; these markers are highly expressed in wide types of cancer 25-27." (PMID 39513121, 2024). "Indeed, we found a significant positive correlation of ALDH1A1 with several gene sets related to cancer progression and metastatic dissemination, including WNT signaling, angiogenesis, osteogenesis, extracellular matrix, and adhesion." (PMID 38169509, 2024). "Notably, we also observed a significant reduction in the protein levels of CD133 and ALDH1A1, markers indicative of cancer stem cells." (PMID 38256104, 2024). "In summarizing our study, CD133 was exclusively expressed in cancer cells compared to stromal and immune cells and was associated with other CSC markers (CD24, NOTCH1, DLL1, and ALDH1A1), as well as enriched WNT/β-Catenin, Hedgehog, and NOTCH signaling, validating CD133 as a CSC marker." (PMID 38585981, 2024). "Additionally, the inhibition of ALDH1A1 reduces the stemness of human and mouse glioblastoma cells by inducing ferroptosis, suggesting a potential strategy for targeting cancer stem cells and overcoming resistance." (PMID 39534872, 2024). "It is also worth noting that in contrast to cancer cells, stromal cells may lose ALDH1A1 during cancer progression." (PMID 37298333, 2023). "In addition to morphological changes, we found a dramatic decrease in tumor sphere formation under BTK inhibition in all the analyzed cell lines, which was accompanied by a significant reduction in the expression of the cancer stemness marker ALDH1A1." (PMID 37685940, 2023). "Furthermore, ALDH1A1-positive cancer cells exhibited important cancer stem cell properties featured by high in vitro tumorigenicity, in vivo tumor initiation and self-renewal capacities, and successively reinitiating transplantable tumors." (PMID 36778142, 2023). "ALDH1A1 also contributes to the further activation of NFκB and aggressive cancer properties." (PMID 37298333, 2023). "ALDH1A1 is also active in platinum-resistant cancer cells residing in hypoxic regions." (PMID 37628927, 2023). "Whether the paired cancer versus normal cells investigated have differentiated to the same degree is also important because the levels of expression of ALDH1A1, ALDH1A2 and ALDH1A3 change during development, and, for example, parallel rat nephron development." (PMID 36768694, 2023). "Also, the close link between erythronate and PPP makes this metabolite a good target for the investigation of PPP and ALDH1A1 activity, which are both relevant for several diseases, including cancer." (PMID 37893215, 2023). "Furthermore, NFATc2/SOX2 coupling can upregulate ALDH1A1 expression, reduce oxidative stress from cancer drug treatment, and increase resistance to chemotherapy and targeted therapy." (PMID 37686694, 2023). "Targeting ALDH1A1-positive cancer cells may be a promising therapeutic strategy, influencing disease course and response to treatment." (PMID 36768723, 2023). "Through modulating ALDH1A1 expression in cancer cell lines, we provide additional support." (PMID 37893215, 2023). "Additionally, some in vitro studies have demonstrated that inhibition of ALDH1A1 leads to increased chemosensitivity of cancer cells." (PMID 36768723, 2023).
cancer (continued). "The role of ALDH1A1 in the retinoic acid signaling pathway is crucial, as it governs the self-renewal and differentiation processes of normal stem cells and also holds significant implications in cancer progression." (PMID 37958210, 2023). "Based on studies of utilizing non-specific ALDH inhibitors and siRNA silencing techniques, inhibition of ALDH1A1 activity might provide new therapeutic options for many diseases, including cancers." (PMID 36484016, 2022). "In terms of intracellular molecular signaling, OCT4 and ALDH1A1 were proved to be the key functional proteins in cancer stem cells, and could be used as cancer stemness markers of RCC cells." (PMID 36319622, 2022). "We reviewed and summarized representative correlative studies and found that ALDH1A1 could induce cancers via the maintenance of cancer stem cell properties, modification of metabolism, promotion of DNA repair." (PMID 35814382, 2022). "Such processes are highly dynamic, and the fate of stem-like state can be decided by ALDH1A1 expression/activity in tumor cells, suggesting that this enzyme might represent a concrete novel target for cancer treatment." (PMID 35299840, 2022). "Several ALDH1A1-based cancer prevention and treatment measures have been developed." (PMID 35814382, 2022). "It was previously reported that ALDH1A1 was upregulated in a drug-tolerant subpopulation of cancer." (PMID 36139693, 2022). "In addition to serving as a stemness marker in malignant tumors, ALDH1A1 also exhibits a key role in the oxidation of retinal to retinoic acid (RA), forming a transcriptional regulator critical for normal cell growth and differentiation." (PMID 36484016, 2022). "ALDH1A1 has been reported to promote cancers of the reproductive system." (PMID 35814382, 2022). "Notably, one of the common markers of normal and cancer stem cells, ALDH1A1, was up-regulated in the CD133+/high population of HT-29 and HUH7 cell, with fold changes of 2.9 and 1.8, respectively." (PMID 36077272, 2022). "However, the expression levels of cancer stemness markers (EpCAM, Nanog and ALDH1A1) were much suppressed in MDA-MB-231 mammospheres (Day 14) in response to Oligo-Fucoidan or the combined treatment than olaparib alone." (PMID 36109724, 2022). "Notably, alcohol dehydrogenase-1 family member A1 (ALDH1A1) is a marker of chemoresistance and cancer stem-like properties in addition to CD44 and CD24." (PMID 35892853, 2022). "ALDH1A1 could induce cancers via the maintenance of CSC properties, modification of metabolism and promotion of DNA repair." (PMID 35814382, 2022). "Platinum-induced secretion of IL-6 from cancer-associated fibroblasts in the tumor microenvironment promotes the enrichment of OCSC in residual tumors after chemotherapy through activation of STAT3 and up-regulation of ALDH1A1 expression." (PMID 36387165, 2022). "ALDH1A1 is also involved in the development of cancers that originate in other systems." (PMID 35814382, 2022). "Cancer studies have investigated roles and functions of these two CSC markers separately in tumor progression, invasiveness and metastases so that high expression of SALL4 and low expression of ALDH1A1 are associated with advanced levels of the disease." (PMID 35090523, 2022). "An increase in the cancer stem cell markers ALDH1A1, SOX2, and NANOG were also observed by PCR." (PMID 35102251, 2022). "ALDH1A1 also acted as a tumor suppressor in certain cancers." (PMID 35814382, 2022). "Likewise, qPCR analysis suggested higher expression levels of CD44, CD133, ALDH1A1, and EpCAM in tumor hybrids than in HepG2 parental cancer cells." (PMID 35562905, 2022). "ALDH1A1 could regulate retinoid signaling via the CEBPB to promote stemness maintenance in cancer stem cells." (PMID 35280765, 2022). "The oligomer-dependent activity of ALDH1A1 signifies that the targeting of its oligomerization state may be an efficient therapeutic approach that could counteract its protective functions in cancer." (PMID 35814382, 2022).
cancer (continued). "Many researchers have developed specific ALDH1A1-targeting drugs that could be used to treat cancer." (PMID 35814382, 2022). "ALDH1A1 plays important roles in various diseases, especially in cancers." (PMID 35814382, 2022). "To determine if DEAR1 plays a role in the regulation of stem/progenitor activity, we examined DEAR1 E6-CshR and E6-DshR HMEC clones for expression of aldehyde dehydrogenase (ALDH1A1), an established marker of stem/progenitor cells that is overexpressed in both normal and cancer stem cells." (PMID 36376460, 2022). "However, the data on the expression of stem cell markers CD44, CD24, and ALDH1A1 in benign breast tissue of cancer-free women remains extremely limited." (PMID 36590957, 2022). "Moreover, dendrimer complexes decreased the expressionlevels of E-cadherin, CD133, and ALDH1A1, hallmarks of cancer aggressivenessand malignancy." (PMID 36445323, 2022). "Additionally, in drug-resistant cell lines, we observed population of ALDH1A1-positive cancer stem cells (CSCs)." (PMID 35008952, 2022). "ALDH1A1 is thought to maintain CSC properties in a variety of cancers." (PMID 35814382, 2022). "Interestingly, PTCH1 shows the highest mutation rate in 7% (127/1867; 7%) of cancers, followed by PDGFRA (89/1867; 5%), ABL1 (68/1867; 4%), FOSB (56/1,678, 3%), ALDH1A1 and CCND2 (48/1,678; 2.9%), (55/1867; 2.9%)." (PMID 36704357, 2022). "Similarly, to positive ALDH1A1 tumors, smaller carcinomas (≤5 cm) more frequently showed positive PD-L1 staining compared to larger tumors (p = 0.004)." (PMID 36139578, 2022). "Moreover, carcinomas with positive ALDH1A1 staining more frequently showed CD20+ cell infiltration compared to negative ALDH1A1 tumors (85% vs. 60%; p = 0.015)." (PMID 36139578, 2022). "ALDH1A1 is a well-known marker of cancer stem cells and a drug resistance promoter in cancer cells." (PMID 35047931, 2021). "As ALDH1A1 is a universal marker of CSCs and piperine has been described to target ALDH1A1+ cancer stem cells, we were interested in whether piperine can influence ALDH1A1 expression in investigated cell lines." (PMID 33921897, 2021). "This could explain the discrepancy in the correlation between ALDH1A1 levels and clinical outcomes in cancer." (PMID 33495566, 2021). "From a pathological standpoint, high levels of ALDH1A1 are often observed in various cancers." (PMID 33495566, 2021). "A recent study conducted on CCA patients showed that high expression of ALDH1A1 correlated with a more favorable prognosis; in many studies, ALDH1A1 is a cancer stem cell marker and a suitable target for therapy and only its activity is associated to worse prognosis." (PMID 34320944, 2021). "This study also demonstrated that the Sox2+ cell population expressing Aldh1a1, a protein associated with a cancer stem cell phenotype, generated tumours in vivo, while this capacity decreased with lower or absent expression of Aldh1a1." (PMID 34445233, 2021). "In addition, we investigated some cancer stem cell markers and we demonstrated an increase in Cd44, Nt5e and Aldh1a1." (PMID 34670568, 2021). "Therefore, yet another metabolic adaptation applied by cancer cells is the reduced rate of synthesis of such metabolites by decreased expression of the ALDH1A1 gene." (PMID 32823815, 2020). "High ALDH1A1 activity has been shown to correlate with CSC phenotype in different cancer types." (PMID 32764385, 2020). "It has been proposed that cancer cells acquire drug resistance by inducing ALDH1A1 expression." (PMID 35582039, 2020). "As is reported, ALDH1A is linked to retinoic acid signaling and all-trans retinoic acid (ATRA), as a potential targeted therapy against cancer stem cells, could inhibit ALDH1A1 activity to improve chemotherapeutic efficacy." (PMID 32293355, 2020). "Moreover, the prognostic value of ALDH1A1 in cancers has been validated by using immunohistochemistry (IHC) on cancer patient tissues." (PMID 35582039, 2020).
cancer (continued). "However, the marker was used successfully to eliminate ALDHbright cells obtained from various cancer cell lines including head and neck, breast, and pancreatic cancer lines in vitro with ALDH1A1-specific CD8+ T cells." (PMID 32391048, 2020). "A similar reason may underlie decreased expression of ALDH1A1 and CD24, cancer stem cell-like markers commonly associated with more aggressive features and EMT phenotype, seen in CR samples." (PMID 32899940, 2020). "ALDH1A1 is highly expressed by malignant CSCs in several cancers." (PMID 32391048, 2020). "Moreover, CD15, CD44, CD166, and ALDH1A1 positivity were each independently associated with a shorter PFS, independently of higher N and cancer stage as well as other clinicopathological factors." (PMID 31428052, 2019). "To elucidate the potential mechanism by which ALDH1A1 inhibition blocks cancer cell proliferation as spheres, we assessed whether CM37 induced DNA damage." (PMID 30965686, 2019). "Therefore, we probed the proteomic data for expression pattern of other well-known cancer stem cell markers such as ALDH1A1 (2.6 fold), CD151 (2.1 fold), CD47 (1.9 fold) and THY1 (3.5 fold)." (PMID 31438645, 2019). "In addition, ALDH1A1 is considered to detoxify metabolic bi-products from chemotherapy and thus conferring cancer resistance in ALDH1A1high cancer cells." (PMID 31106150, 2019). "Moreover, SCD1 depletion induced a reduction in ALDH1A1 activity, a marker of cancer stem cells, determining apoptosis specifically in ALDH1A1-positive cells." (PMID 31717588, 2019). "Moreover, ALDH1A1 isozyme has been shown to play an important functional role in maintaining cancer stem cells." (PMID 31315286, 2019). "Additionally, the lower PTPRK expression was observed in Aldehyde Dehydrogenase 1 Family Member A1 (ALDH1A1) positive cancer stem cells (CSCs) population, suggesting the role of PTPRK downregulation in primary as well as acquired resistance to cytotoxic drugs." (PMID 31027318, 2019). "Moreover, DDC inhibited ALDH1A1 activity (by 50%, ki) in normal and cancer hepatocytes at 23.29 ± 1.3 and 27.04 ± 3.6 μg/ml, respectively." (PMID 29545617, 2018). "More importantly, here we show the link between ALDH1A1 and tumorigenic potential of cancer cells." (PMID 29902974, 2018). "Further, enhancement of HIF-1α observed in MCF-7 ALDH1A1+ is consistent with the higher tumor growth by the reprogramming of metabolism of tumor cells toward an oxygen-independent biochemical pathway and the sustainment of stemness property in many cancers." (PMID 30541574, 2018). "The increased expression of ECM genes/proteins by ALDH1A1 positive cells gives evidence that cancer cells exposed to paclitaxel and topotecan are able to develop a new mechanism of drug resistance combining the models known so far as separate ones (CSCs and ECM)." (PMID 30583585, 2018). "Apart from research in ALDH1 (ALDH1A1) in cancer stem cells, in fact, research interests in ALDH have been greatly increased recently, especially, ALDH2, because ALDH2 is the most efficient enzyme for the metabolism of ethanol-derived acetaldehyde with the lowest Km." (PMID 29552329, 2018). "High expression of ALDH1A1 has been reported in several tumor and cancer cell lines." (PMID 28129349, 2017). "Functionally, forced expression of miR-23b could disrupt cancer stemness via suppressing ALDH1A1 expression while addition of miR-23b inhibitor bore the ability to increase cancer stem cells population." (PMID 28449663, 2017). "In addition, these cells were also positive for the cancer stem cell markers, Aldehyde Dehydrogenase 1 (ALDH1A1) and CD44 suggesting that these cells display some characteristics of stem-ness." (PMID 29187162, 2017). "Our findings support the possibility that combining retinaldehyde with drugs that inhibit ALDH1A1 might offer potential benefit for cancer treatment." (PMID 29245909, 2017). "Increased ALDH1A1 levels and activity are hallmarks of cancer stem cells." (PMID 28193222, 2017).
cancer (continued). "Notably, when ALDH1A1 expression was decreased, there was a significant sensitization of the cancer cells to both chemotherapy and radiation." (PMID 28937653, 2017). "Recent global phospho-proteomic screens have revealed increased phosphorylation of ALDH1A1 at the T267 site in human cancers and healthy liver tissues where ALDH1A1 is highly expressed and active, indicating that this regulation is likely crucial both in normal and diseased states." (PMID 28193222, 2017). "This is also the first study to demonstrate oligomer-dependent activity of ALDH1A1, signifying that targeting its oligomerization state may be an effective therapeutic approach for counteracting its protective functions in cancer." (PMID 28193222, 2017). "Thus, there is a critical need to develop therapies that target ALDH1A1 alone or in combination to eliminate these “stem cell-like” tumor cells in pancreatic and other types of cancer." (PMID 28193222, 2017). "As expected, the ALDH1A1-positive cancer cells are more rarely observed, which is consistent with the cancer stem cell hypothesis." (PMID 29245982, 2017). "While several studies have shown increased mRNA or protein levels of ALDH1A1 in different cancers, the molecular mechanism remains unclear." (PMID 28193222, 2017). "ALDH1A1/3A1 are often over-expressed in cancers, but their function in cancer still remains unclear." (PMID 28978015, 2017). "However, for future cancer treatment, further studies are needed that identify specific ALDH1A1 inhibitors or inhibitors of other ALDH involved in CSC regulation without off-target toxicity." (PMID 26783961, 2016). "Despite accumulating evidence in several cancers for the functional role of ALDH1A1 enzyme in CSC self-renewal and survival, the specific mechanisms involved in its regulation in CSCs remain unclear." (PMID 27448961, 2016). "Thus, we should be careful in reviewing AlDH1A1 overexpression and high activity in various cancer types." (PMID 26783961, 2016). "In the present study, double immunofluorescence staining of these stem/progenitor cell markers showed that a small number of cells coexpressed CD44v6 and ALDH1A1, which may be indicators of cancer stem cells in NPC." (PMID 27647953, 2016). "ALDH1A1 also plays a vital role as a marker of SCs and cancer stem cells (CSCs)." (PMID 26783961, 2016). "Furthermore, only in the malignancies, we can observed high levels of ALDH1A1, and in particular in the CSCs in relation to their capacity to protect the other differentiated cancer cells." (PMID 27651797, 2016). "Furthermore, in low-grade esophageal squamous dysplasia, ALDH1A1-positive cells were distributed in the basal layer of the mucosa, suggesting normal mucosal stem cells as the source of cancer stem-like cells." (PMID 26783961, 2016). "ALDH1A1 and CD44v6 double-positive cells were observed in the cancer nest in the merged image." (PMID 27647953, 2016). "The modulation of ALDH1A1 might also play a key role in the regulation of growth and differentiation of both normal and cancer cells, also influencing some aspects of the cancer phenotype and prognosis." (PMID 26783961, 2016). "ALDH1A1 levels appear to be positively correlated with the prognosis of various cancers, although a combined assessment may better improve their prognostic potential." (PMID 27152521, 2016). "In the RNS-rich microenvironment, ALDH1A1-positive stem cells with nitrative DNA damage might become cancer stem cells expressing CD44v6, which plays a major role in stem cell maintenance and nuclear reprogramming." (PMID 27647953, 2016). "Such diminished tumorigenicity could be due to a reduction in the number of cancer stem-like cells present in sh-AhR + sh-Aldh1a1 cultures and/or to a less undifferentiated status." (PMID 26242870, 2015).